SREK1IP1 (SREK1 interacting protein 1)
Description:
Possible splicing regulator involved in the control of cellular survival.
Synonyms: p18SRP; SFRS12IP1; FLJ36754
Tractability: PROTAC: ubiquitination databases record sites on it.
Gene: Protein-coding gene on chromosome 5 (64,718,148 to 64,768,692, reverse strand). Ensembl gene ENSG00000153006.
Subcellular location (Human Protein Atlas): Nucleoli; Nucleoplasm
Gene Ontology:
Molecular function: protein binding; nucleic acid binding; zinc ion binding
Genetic constraint (gnomAD): Loss-of-function variants: 10 observed, 18.11 expected, observed/expected ratio (o/e) 0.55, 90% interval 0.34 to 0.94. The upper end of that interval is the gene's LOEUF score, 0.94, which puts it in group 3 of 6, group 1 being the genes least tolerant of losing a copy. Missense variants: 142 observed, 154.82 expected, observed/expected ratio (o/e) 0.92, 90% interval 0.8 to 1.05. Synonymous variants: 53 observed, 48.37 expected, observed/expected ratio (o/e) 1.1, 90% interval 0.88 to 1.38.
Homologues: Orthologues: chimpanzee SREK1IP1 (100% identical), macaque SREK1IP1 (99% identical), dog SREK1IP1 (95% identical), guinea pig SREK1IP1 (94% identical), pig SREK1IP1 (94% identical), rabbit SREK1IP1 (94% identical), mouse Srek1ip1 (88% identical), rat Srek1ip1-ps1 (88% identical), rat Srek1ip1 (86% identical), tropical clawed frog srek1ip1 (61% identical), zebrafish srek1ip1 (46% identical), Caenorhabditis elegans C13F10.7 (32% identical).
Diseases named in the same sentence as SREK1IP1 in open-access papers:
SREK1IP1 is named in the same sentence as 2 diseases in open-access papers, as found by Europe PMC text mining. Sharing a sentence is not in itself a finding about the gene and the disease. The quoted sentences say what the papers report.
tumor (1 paper, 2016). "Among them, we selected five decreased (CCDC28B, SREK1IP1/P18SRP/SFRS12IP1, RASL10B, PHF21A/BHC80 and PGC) and two increased genes (IL-11 and CXCL2), by microarray, as differentiation-, splicing-, inflammation-, or tumor-related genes." (PMID 26701885, 2016).
SREK1IP1 also shares sentences with these, for which no sentence is quoted: colon cancer (1 paper).